OXTR (oxytocin receptor)
Diseases named in the same sentence as OXTR in open-access papers (continued):
Sharing a sentence is not in itself a finding about the gene and the disease.
Obesity (35 papers, 2011 to 2025). Accumulation of substantial excess body fat. "OXT- and OXTR-knockout models reproduce hallmark features seen in humans, including obesity, anxiety-like behavior, social avoidance, and impaired maternal care." (PMID 41614746, 2025). "Common variants in the oxytocin receptor gene (OXTR) have been associated with socially-related personality traits and behaviours, and obesity pathogenesis." (PMID 40956856, 2025). "The present study demonstrates that KKT ameliorates chronic inflammation, which is strongly associated with aging and obesity, and decreases food intake in male mice as well as sucrose intake in female mice; in an oxytocin receptor dependent manner." (PMID 38742193, 2024). "Considering the other identified genes, targeting OXTR, which encodes a protein that mediates anabolic skeletal recovery, has been suggested as a possible therapeutic target for osteoporosis and obesity." (PMID 35580864, 2022). "For instance, a case study associated an OXTR gene duplication with pervasive developmental disorder, especially obesity and behavioral issues." (PMID 34980886, 2022). "Oxytocin receptor or OT deficient mice are associated with adult-onset obesity that appears at 8, 10 or 16 weeks in OT null mice and 12 weeks in OTR null mice." (PMID 34720864, 2021). "Metabolic perturbations, including decreased energy expenditure and/or decreased muscle tonicity, are thought to drive obesity in normophagic oxytocin/OXTR-deficient mice." (PMID 34299356, 2021). "The striking evidence that Oxt is linked to energy regulation is that Oxt- and oxytocin receptor (Oxtr)-deficient mice show a phenotype characterized by late onset obesity." (PMID 32708109, 2020). "Animal studies have revealed that both PGC-1α knock-out and oxytocin receptor-deficient mice exhibit similar abnormalities and impaired thermoregulation and obesity." (PMID 28077341, 2017). "The oxytocin receptor (OXTR) gene, particularly the polymorphisms rs53576 and rs2254298, has been studied in relation to social behaviour, stress reactivity, eating patterns, and obesity." (PMID 40956856, 2025). "Moreover, the striking evidence that Oxt is linked to energy regulation is that Oxt- and Oxytocin receptor (Oxtr)-deficient mice show late onset obesity." (PMID 34203705, 2021). "CCKA receptor-deficient mice and rats 31,65, PrRP-deficient mice 18 and oxytocin receptor-deficient mice 66 all show an increased meal size and late-onset obesity, suggesting the importance of the CCK–PrRP–oxytocin pathway in the control of food intake, especially in the termination of each meal." (PMID 23363338, 2013). "Other genes such as MC4R, leptin and leptin receptor, Ghrelin (GHRL), peroxisome proliferator-activated receptor gamma (PPARG), oxytocin receptor (OXTR), prohormone convertase-1 and proopiomelanocortin have been implicated in human obesity and will be discussed elsewhere in this journal issue." (PMID 22043167, 2011). "The activation of the oxytocin receptor pathway by means of infusion of oxytocin, oxytocin analogs, or oxytocin agonists may additionally constitute a promising approach for the control of obesity and associated metabolic illnesses in addition to diabetes and its complications." (PMID 35462799, 2022). "Interestingly, oxytocin- and oxytocin receptor-deficient mice develop late-onset obesity with normal food intake, suggesting that the hormone might exert a series of beneficial metabolic effects." (PMID 21980491, 2011). "Animal models with OXT or OXTR knockout consistently show late-onset obesity, reduced thermogenesis, and lower energy expenditure, highlighting OXT’s role in metabolic homeostasis." (PMID 41614746, 2025). "Immunohistochemical analysis further revealed increased OXTR expression in bladder tissues from obese rats, adding mechanistic insight into obesity-related bladder dysfunction." (PMID 41007660, 2025).
Obesity (continued). "Oxytocin receptor (OXTR) upregulation has been proposed to enhance bladder and prostate contractility, while obesity is a recognized risk factor for LUTS, OAB, and BPH." (PMID 41007660, 2025). "It is well established that obesity increases OXTR mRNA expression level in adipose tissue and the brain, an observation further supports by our own finding that HFD feeding increases OXTR mRNA expression in adipose tissue." (PMID 38742193, 2024). "Nevertheless, OXTR abnormalities are also connected to other diseases, including cancer, cardiac disorders, osteoporosis, and obesity." (PMID 36835321, 2023). "Investigations of changes in the levels or functions of OXT and/or OXTR also apply to cancer, osteoporosis, and obesity, as well as viral infections or cardiac disorders." (PMID 36835321, 2023). "The effect of obesity on oxytocin receptor protein and mRNA expression in adipose tissue was evaluated by Western blotting and real-time polymerase chain reaction." (PMID 32819381, 2020). "To better understand the potential biomolecular mechanisms by which obesity could affect myometrial function, we investigated myometrial gene and protein expression of OXTR and FP receptor." (PMID 39060750, 2024). "Oxytocin and OXTR mediated signaling also has strong anti-obesity effects." (PMID 38742193, 2024). "We hypothesized that myometrial tissue from term individuals with obesity have reduced expression of the OXTR and FP and decreased contractility compared with samples from normal-weight individuals." (PMID 39060750, 2024). "Since KKT moderately activates OXTR, the effect of KKT may be amplified when OXTR expression is upregulated in conditions such as inflammation, obesity, aging and under the condition that plasma oxytocin becoming low." (PMID 38742193, 2024). "Both OXTR- and oxytocin-deficient mice developed obesity, without changes in food intake and locomotor activity, suggesting that the physiological role of oxytocin is to increase energy expenditure." (PMID 38742193, 2024). "OXTR expression on adipocytes is increased in the state of obesity and may have a role in counteracting the inflammatory response associated with excess weight." (PMID 34299356, 2021). "Given that systemic inflammation has been associated with the pathophysiology of obesity and T2D, the anti-inflammatory actions of OXT/OXTR may also be important in attenuating disease progression." (PMID 32819381, 2020). "Since obesity has been described as a state of chronic inflammation, dysfunction of the OXT/OXTR system may exacerbate inflammatory diseases/disorders related to obesity such as hypertension, diabetes, and heart disease." (PMID 32819381, 2020). "For example, OXTR and OXT deficient mice exhibit late onset obesity and insulin resistance." (PMID 32819381, 2020). "As summarized in this review, the changes related to OXTR significantly influenced the course of various diseases, from reproductive system diseases and through mental disorders, mucopolysaccharidoses, cancer, and cardiovascular diseases to others (such as osteoporosis and obesity)." (PMID 36835321, 2023). "Notably, Oxytocin are also reported to regulate fat accumulation, OXTR-deficient mice show an increase of white adipose Tissue (WAT) and a decrease of body temperature compared with controls, implying that the absence of OXTR might increase the likelihood for overweight and obesity." (PMID 39974186, 2025). "Some assurance for a role in metabolism arrived when it was discovered that mice lacking the oxytocin receptor exhibit late‐onset obesity." (PMID 34495565, 2021). "In addition, because OXT KO mice and OXTR KO mice show significantly increased body weight, the OXT/OXTR system appears to be strongly involved in obesity and/or control of food intake." (PMID 32719656, 2020).
Obesity (continued). "Prader–Willi syndrome (PWS), which is also associated with a depletion of hypothalamic oxytocin producing neurons as well as a reduction in the peripheral expression of the OXTR in humans, presents with hyperphagia, lack of satiety, obesity, hypotonia, and unfavorable body composition." (PMID 34299356, 2021). "Further, we did not investigate whether diet or maternal obesity affect levels of oxytocin receptor expression or sensitivity, in the brain or the periphery." (PMID 35222059, 2021). "Mice lacking oxytocin or oxytocin receptor display late onset obesity with normal food intake." (PMID 23028821, 2012).
schizophrenia (33 papers, 2012 to 2025). A major psychotic disorder characterized by abnormalities in the perception or expression of reality. "For example, a recent study in schizophrenia demonstrated that OXTR polymorphisms moderated the impact of childhood trauma on social functioning." (PMID 41356682, 2025). "Alterations in OXTR have been implicated in several neuropsychiatric disorders, including autism spectrum disorder, depression, schizophrenia, and obsessive–compulsive disorder, although cross-population findings remain inconsistent." (PMID 40565372, 2025). "We found that OXTR rs2268490 was associated with schizophrenia patients’ treatment responses to antipsychotics." (PMID 38184684, 2024). "Overall, our results highlighted the possibility of nominally significant associations of the OXTR gene with the severity and improvement in schizophrenia symptoms." (PMID 38184684, 2024). "Regarding treatment responses in schizophrenia, our results showed that OXTR rs2268490 presented a nominal association with the improvement in negative symptoms apathy/avolition." (PMID 38184684, 2024). "In our study, OXTR rs237899 was found to be associated with the severity of overall symptoms of schizophrenia." (PMID 38184684, 2024). "Other studies have shown a significant association between emotional withdrawal typical of schizophrenia and the rs53576 oxytocin receptor gene variant." (PMID 35888641, 2022). "A recent study of early-stage schizophrenia also demonstrated that hypomethylation status at the same genomic OXTR position as our significant results was associated with susceptibility to schizophrenia and anhedonia-asociality in women." (PMID 32631409, 2020). "We additionally wanted to replicate findings regarding SNPs found to be associated either to schizophrenia or social behavior-related psychopathology (OXTR SNPs rs53576, rs2254298, and rs237902) in several previous studies." (PMID 25667571, 2015). "SNPs of the OXTR gene are associated with the severity of symptoms and the improvement of the positive symptoms of schizophrenia following treatment with antipsychotics." (PMID 26089815, 2015). "For this reason, no final statement can be made about a possible contribution of OXTR rs2254298 polymorphisms to schizophrenia vulnerability so far." (PMID 23284802, 2012). "As for OXTR rs2254298, A-allele frequencies were 0.11 in the schizophrenia and 0.10 in the healthy sample; for OXTR rs53576, A-allele frequencies were 0.32 in the schizophrenia and 0.29 in the healthy sample." (PMID 23284802, 2012). "In conclusion, we give tentative evidence on the involvement of OXTR genetic variants in empathic functioning in schizophrenia." (PMID 23284802, 2012). "We tested for the associations between OXTR polymorphisms and symptoms of schizophrenia." (PMID 38184684, 2024). "Besides, OXTR polymorphisms have been found to be associated with improvement in symptoms of schizophrenia following antipsychotic agents." (PMID 38184684, 2024). "Second, most previous studies were conducted in the European population and it can be expected that some of the findings about the associations between the OXTR gene and schizophrenia may be population-specific." (PMID 38184684, 2024). "Furthermore, the analyses of symptom subdomains of schizophrenia revealed that OXTR rs237899 was associated with the severity of hostility symptoms of schizophrenia patients." (PMID 38184684, 2024). "To further investigate how OXTR polymorphisms impact on severity of multidimensional symptoms of schizophrenia and responses to antipsychotics, we did a study on 2363 patients of Han Chinese ancestry with schizophrenia." (PMID 38184684, 2024). "However, previous studies on the association between OXTR polymorphisms and schizophrenia usually focused on general symptoms but specific symptoms, studied limited antipsychotics, and had small sample sizes." (PMID 38184684, 2024).
schizophrenia (continued). "The findings suggested that dysfunctions of OXTR including downregulation expression and genetic variants correlated with schizophrenia, which might contribute to the impairments of social cognition." (PMID 37153633, 2023). "Epigenetic changes in the OXTR gene were also reported as being associated with schizophrenia." (PMID 36835321, 2023). "The single-nucleotide polymorphisms of the oxytocin receptor gene could profoundly affect treatment-refractory symptoms by mediating social cognitive processes in persons with schizophrenia." (PMID 35806096, 2022). "OXTR SNPs have however been found to be associated with clinical symptomatology in patients with schizophrenia, including general psychopathology (rs53576 and rs2254298), negative symptoms as measured by the Positive and Negative Syndrome Scale (PANSS) (rs237902), and empathic concern (rs2254298)." (PMID 25667571, 2015). "Our findings might corroborate previous research indicating a possible genetic contribution of OXTR polymorphisms a) to social cognitive functioning and empathy and possibly b) to schizophrenia risk and psychopathology." (PMID 23284802, 2012). "Besides, the evidence of previous studies and the QTL effects of OXTR variants may support plausible explanations of the associations between OXTR polymorphisms and schizophrenia." (PMID 38184684, 2024). "Therefore, OXTR polymorphisms may influence the severity and treatment responses of schizophrenia symptoms by interactions with the dopamine system." (PMID 38184684, 2024). "Given the exploratory nature of this study, these associations are indicative of the role of the OXTR gene in the pathology of schizophrenia and may contribute to further elucidate the mechanism of specific symptoms of schizophrenia and to exploit antipsychotics more effective to specific symptoms." (PMID 38184684, 2024). "Beside the single report of being associated with schizophrenia, OXTR rs53576 was suggested to mediate dispositional empathy, social stress reactivity, prosocial attitude, social support seeking and trust, while OXTR rs2254298 was associated with cognitive empathy in healthy individuals." (PMID 23284802, 2012). "To explore the biological plausibility of OXTR in the pathogenesis of schizophrenia, we made eQTL and mQTL analyses using the BRAINEAC and PhenoScanner databases." (PMID 38184684, 2024). "On the other hand, higher OXTR mRNA levels were detected in leukocytes of first-episode schizophrenia patients than in healthy persons." (PMID 36835321, 2023). "When the role of OXTR in schizophrenia was tested, it was demonstrated that in the brains (particularly in the temporal cortex) of patients (tested post-mortem), the levels of mRNA of the OXTR gene were significantly decreased relative to the control samples." (PMID 36835321, 2023). "Recent studies have found that genetic polymorphisms in the OXTR and OXT genes in humans have been significantly related to schizophrenia and that OXTR and OXT gene variants have been involved in schizophrenia vulnerability and warrant independent replication." (PMID 37153633, 2023). "Reduced OXTR gene expression in the temporal cortex and binding sites in the vermis were found in schizophrenia patients compared to healthy controls." (PMID 37153633, 2023). "Positive associations have been found between OXTR DNA methylation and affect regulation problems and mood deficits, OCD severity, schizophrenia, anorexia nervosa, callous-unemotional traits in youth and social cognitive and communication deficits in ASD." (PMID 35688807, 2022). "OXT and AVPR1a gene expression at both the mRNA and protein levels were significantly lower in the schizophrenia group, and OXTR and AVP gene expression at both the mRNA and protein levels was higher in the schizophrenia subjects than in the controls." (PMID 35723404, 2022).